SRPX (sushi repeat containing protein X-linked)
Description:
May be involved in phagocytosis during disk shedding, cell adhesion to cells other than the pigment epithelium or signal transduction.
Synonyms: ETX1; SRPX1; DRS; HEL-S-83p
Tractability: Antibody: UniProt places it where antibodies can reach, with high confidence; UniProt predicts a signal peptide or a membrane-spanning region.
Gene: Protein-coding gene on chromosome X (38,149,336 to 38,220,941, reverse strand). Ensembl gene ENSG00000101955.
Subcellular location: Cell surface
Gene Ontology:
Molecular function: protein binding; extracellular matrix structural constituent
Biological process: phagolysosome assembly
Cellular component: extracellular matrix; membrane; cell surface
Homologues: Orthologues: chimpanzee SRPX (100% identical), pig SRPX (95% identical), macaque SRPX (94% identical), rat Srpx (93% identical), mouse Srpx (93% identical), guinea pig SRPX (92% identical), tropical clawed frog srpx (69% identical), rabbit SRPX (65% identical), zebrafish srpx (58% identical). Paralogues in human: SRPX2 (45% identical), CFH (21% identical), F13B (17% identical), CFHR5 (16% identical), CSMD3 (16% identical), CSMD1 (15% identical), PAPPA (15% identical), CSMD2 (14% identical), PAPPA2 (14% identical), SVEP1 (14% identical), CFHR3 (13% identical), SEZ6L (13% identical), and 27 more.
Diseases named in the same sentence as SRPX in open-access papers:
SRPX is named in the same sentence as 30 diseases in open-access papers, as found by Europe PMC text mining. Sharing a sentence is not in itself a finding about the gene and the disease. The quoted sentences say what the papers report.
ovarian carcinoma (7 papers, 2021 to 2025). A malignant neoplasm originating from the surface ovarian epithelium. "The study observed a significant increase in the expression of the SRPX gene in cancer-associated fibroblasts of high-grade serous carcinoma, clear cell carcinoma, and ovarian carcinoma." (PMID 38555418, 2024). "SRPX has been reported to regulate cancer-associated fibroblasts to promote the invasiveness of ovarian carcinoma." (PMID 34276767, 2021). "The overexpression of SRPX has been affirmed by a recent study based on clinical specimens, wherein the upregulation of SRPX is associated with tumor invasion and migration activity in ovarian cancer." (PMID 34917619, 2021). "SRPX also regulates the migration and invasion of ovarian cancer through the Ras homolog family member A signaling pathway." (PMID 39010084, 2024). "Some studies have shown that SRPX is related to the short OS time of endometrial cancer, and can regulate tumor-related fibroblasts and promote the invasiveness of ovarian cancer." (PMID 35548187, 2022). "Knocking down of SRPX via shRNA technology resulted in significant inhibition of ovarian cancer cell migration." (PMID 35454889, 2022). "Additionally, recent studies pointed out a critical role of SRPX in cell migration and invasion of ovarian cancer cells." (PMID 35454889, 2022). "However, one difference is worth noting: we found that SRPX was overexpressed in most rules for ovarian cancer." (PMID 34917619, 2021).
glioblastoma (4 papers, 2010 to 2025). The most malignant astrocytic tumor (WHO grade IV). "Taken together, our results suggest that SRPX can be used as a novel tumor biomarker for diagnostic and prognostic purposes for glioblastomas." (PMID 35454889, 2022). "Strikingly, sushi repeat-containing protein, X-linked (SRPX) was the only protein detected in the majority of glioblastoma-derived EVs (three out of four cell line EVs) that was absent in the HPA-derived EVs." (PMID 35454889, 2022). "Taken together, the results of this study suggest that SRPX can be used as a novel tumor marker for diagnostic and prognostic purposes and can also be a therapeutic target for glioblastomas." (PMID 35454889, 2022). "In this study, we used proteomics analysis to discover a novel tumor biomarker in glioblastoma human primary cell-derived EVs and found that sushi-repeat containing protein X-linked (SRPX) was the only protein identified in the majority of glioblastoma EVs that was absent in the HPA-derived EVs." (PMID 35454889, 2022). "We also found that TMZ treatment of glioblastoma cells showed a significant increase in the SRPX mRNA levels in a dose-dependent manner." (PMID 35454889, 2022). "Taken together, these findings suggest that SPRX is involved in TMZ metabolism, and further studies are required to describe the exact mechanism by which SRPX regulates TMZ metabolism in glioblastomas." (PMID 35454889, 2022). "Our observation of high SRPX staining in TMZ resistant tumor samples triggered us to further evaluate the possible role(s) of SRPX in TMZ metabolism in glioblastomas." (PMID 35454889, 2022). "SRPX, in contrast, was present in most of the glioblastoma-derived EVs and was absent in HPA-derived EVs, therefore, in this study we focused on SRPX and investigated its possible role as a tumor biomarker in glioblastoma tumorigenesis." (PMID 35454889, 2022). "We identified that SRPX was the only protein enriched in the majority of glioblastoma cell line EVs (three out of four cell lines EVs) that was absent in the HPA-derived EVs." (PMID 35454889, 2022). "Taken together, our findings demonstrated that SRPX is highly enriched in glioblastoma EVs and provided insight into the clinical relevance of how this unique tumor marker could contribute to the early detection of glioblastomas." (PMID 35454889, 2022). "Then, we evaluated the relationship between SRPX protein expression and tumor grade using immunohistochemical staining (IHC) and performed colony formation and viability assays to analyze the possible function of SRPX in glioblastoma." (PMID 35454889, 2022). "We next performed a cell viability assay, in order to investigate whether SRPX knockdown sensitizes resistant glioblastoma cells to TMZ." (PMID 35454889, 2022). "In conclusion, these results show that SRPX is expressed at higher levels in glioblastoma tumors, suggesting that SRPX might play a crucial role in glioblastoma tumorigenesis." (PMID 35454889, 2022). "In light of these observations and our proteomics data, we hypothesized that SRPX may be a disease marker for glioblastomas." (PMID 35454889, 2022). "Taken together, these results show that SRPX reduces cell viability in glioblastoma cell lines." (PMID 35454889, 2022). "Moreover, we further analyzed the possible role of SRPX in glioblastoma tumorigenesis and found that SRPX is involved in glioblastoma cell growth, and SRPX depletion sensitizes glioblastoma to temozolomide (TMZ)." (PMID 35454889, 2022). "Taken together, our results show that SRPX depletion sensitizes glioblastoma cell lines to TMZ." (PMID 35454889, 2022). "However, the reduction in HEK 293T cells was considerably smaller following siRNA treatment (~15% non-viable), and not significantly different from control siRNA treated or untreated controls, suggesting a specific role of SRPX in glioblastoma tumorigenesis." (PMID 35454889, 2022).
glioblastoma (continued). "We used mass spectrometry to analyze proteomics profiles of EVs derived from four glioblastoma cell lines and human primary astrocytes (HPAs) and found that SRPX is the only protein enriched in the majority of glioblastoma EVs that was absent in the HPA-derived EVs." (PMID 35454889, 2022). "We next asked a question about whether SRPX plays a role in cell growth of glioblastoma cells, and performed several experiments using glioblastoma cells and HEK293T cells as controls." (PMID 35454889, 2022). "Additionally, glioblastoma cells displayed enhanced SRPX gene expression when exposed to TMZ." (PMID 35454889, 2022). "Moreover, SRPX depletion via siRNA sensitizes glioblastoma cell lines to TMZ." (PMID 35454889, 2022). "Notably, SRPX is among the soluble factors secreted by core-like glioblastoma cells and is assumed to contribute to intercellular signaling between core- and edge-like glioblastoma cells." (PMID 35454889, 2022). "Thus, our results suggest that SRPX is a marker for glioblastoma." (PMID 35454889, 2022). "Furthermore, our study highlights the role of SRPX in glioblastoma tumorigenesis." (PMID 35454889, 2022). "To validate the proteomics findings, we performed immunohistochemical staining on glioma Grade 2–4 tumors, which revealed that glioblastoma and TMZ-resistant recurrent tumors had the highest SRPX protein levels." (PMID 35454889, 2022). "Previous efforts to characterize the proteome of EVs released from glioblastoma cells, as well as 60 human cancer cell lines (NCI-60), revealed the presence of the SRPX protein in cancer cell EVs." (PMID 35454889, 2022).
prostate carcinoma (3 papers, 2018 to 2024). A carcinoma that arises from epithelial cells of the prostate gland. "The second lowest p-value was for a variant upstream of the SRPX (p-value = 2.18e-4) gene which has previously been shown to have a tumor suppressor function in prostate carcinomas." (PMID 30713548, 2018).
breast carcinoma (2 papers, 2022 to 2025). "A recent study showed that breast cancer cell lines resistant to trastuzumab emtansine have higher SRPX mRNA levels compared to naïve cells." (PMID 35454889, 2022).
colorectal cancer (2 papers, 2022 to 2024). A primary or metastatic malignant neoplasm that affects the colon or rectum. "In informatic analyses, SRPX has been used to construct a model for predicting the prognosis of colorectal cancer and is another hypoxia-related signature for prognosis prediction in head and neck squamous carcinoma." (PMID 38500661, 2024). "In colorectal cancer, SRPX was used for the establishment of the prognostic model." (PMID 36452497, 2022).
liver cancer (2 papers, 2017 to 2022). An epithelial or non-epithelial malignant neoplasm that arises from the liver. "Moreover, SRPX has been shown to be a cancer stem cell marker related to chemoresistance in liver cancer." (PMID 35454889, 2022).
cerebral amyloid angiopathy (1 paper, 2022). "A pioneering study on SRPX revealed SRPX deletion in patients with X-linked retinitis pigmentosa, and a recent study revealed that SRPX is a novel disease-associated molecule in cerebral amyloid angiopathy." (PMID 35454889, 2022).
gastric cancer (1 paper, 2016). A primary or metastatic malignant neoplasm involving the stomach. "There are few studies on LCAT and SRPX in cancer metastasis, with only one reported that SRPX is upregulated in gastric cancer cells after depletion of TWIST, which promoted the epithelial-mesenchymal transition that occurs during the initial steps of tumour metastasis." (PMID 27567667, 2016).
glioma (1 paper, 2022). A benign or malignant brain and spinal cord tumor that arises from glial cells (astrocytes, oligodendrocytes, ependymal cells). "In the smaller dataset, which includes all gliomas, SRPX mRNA expression was higher in Grade 4 samples, but the differences among the groups were not statistically significant." (PMID 35454889, 2022).
head and neck squamous cell carcinoma (1 paper, 2022). A squamous cell carcinoma that arises from any of the following anatomic sites: lip and oral cavity, nasal cavity, paranasal sinuses, pharynx, larynx, and salivary glands. "SRPX enriched in EVs has been suggested to have a crucial role in matrix and membrane remodeling in drug resistance, in head and neck squamous cell carcinoma." (PMID 35454889, 2022).
lung carcinoma (1 paper, 2010). "Reintroduction of SRPX into lung cancer cell line from SRPX knock-out mice led to the suppression of tumor formation, accompanied by enhanced apoptosis." (PMID 20964819, 2010). "Of note, 30% of SRPX knock-out mice developed various tumors: lymphoma, lung cancer, hepatoma, sarcoma, while no tumors appeared in the control wild-type mice." (PMID 20964819, 2010).
prostate tumors (1 paper, 2019). "Decreased expression of these genes significantly discriminates between recurrent and non-recurrent prostate tumors from the Cancer Genome Atlas (TCGA) cohort (n = 423), and ASB2, NUDT10, and SRPX were significantly correlated with lower recurrence-free survival in patients by Kaplan-Meier analysis." (PMID 30917865, 2019).
rectal cancer (1 paper, 2022). A primary or metastatic malignant neoplasm that affects the rectum. "In conclusion, a hypoxia score based on 5 hypoxia-related genes can be used to predict the prognosis of rectal cancer and ANLN with a cancer-suppressing effect and SRPX (Sushi Repeat Containing Protein X-Linked) with a cancer-promoting effect may be potential therapeutic targets for rectal cancer." (PMID 35548187, 2022). "Our study found that SRPX is almost not expressed in neutrophils and highly expressed in HRisk, which is associated with the poor prognosis of rectal cancer." (PMID 35548187, 2022). "SRPX may play the role of cancer-promoting factor in hypoxia-mediated progression of rectal cancer, promote neutrophils, and inhibit the immune function of T cells." (PMID 35548187, 2022). "At present, no one has reported the role of SRPX in rectal cancer." (PMID 35548187, 2022).
tumor (25 papers, 2010 to 2025). "Consequently, promoting SRPX mRNA expression is closely linked to inhibiting tumor progression and promoting senescence." (PMID 38650467, 2024). "SRPX mRNA and protein expression were associated with tumor grade." (PMID 35454889, 2022). "In GC, SRPX has been identified as a potential tumor marker, with its expression levels correlating with tumor progression and metastasis." (PMID 40729021, 2025). "Of note, we confirmed a correlation between the expression levels of perlecan/HSPG2 and LAMB3 or HSPG2 and SRPX and found that it increases during tumor progression." (PMID 39149513, 2024). "For example, SRPX is a tumor-suppressor gene that was reported to be downregulated in a variety of human tumor cells and tissues." (PMID 39175079, 2024). "A study showed that SRPX expression is increased in senescent cells and decreased in tumor cells, and SRPX itself promotes angiogenesis through the FAK pathway." (PMID 36945046, 2023). "Tregs were recognized as a subset of T cells that suppresses immunity in sterilization and anti-tumor, thus SRPX and IL6 can be a novel target for recovering immune response in EC tumor cells." (PMID 36675190, 2023). "We also found that ARL4C and HOXC8 were upregulated, and FABP4, PCOLCE2, SERPING1, and SRPX were downregulated in tumor tissue compared to corresponding healthy tissue." (PMID 35664768, 2022). "The role of SRPX in cancer was first reported on v-src (drs) studies, the mouse homolog of SRPX, which implied a tumor-suppressor role for this gene." (PMID 35454889, 2022). "On the contrary, in the larger dataset, Grade 4 tumor samples had higher SRPX mRNA expression compared to Grade 3 samples." (PMID 35454889, 2022). "SRPX (ENSG00000101955) is reported to be a tumor-suppressor gene and is downregulated in multiple cancer cells and tissues." (PMID 34917619, 2021). "The SRPX gene acts as a tumour-suppressor gene, which is down-regulated in several malignancies, including PRAD, COAD, READ, and neuroendocrine (cells that release hormones into the blood in response to stimulation of the nervous system) cancers." (PMID 34681112, 2021). "Of the remaining genes there is no established relation to pemetrexed or platinum resistance, but PMP22, SRPX are indicators of increased tumour progression and/or aggressivity in other cancers." (PMID 22905093, 2012). "However, the model requires further refinement, particularly in elucidating the underlying biological mechanisms of ATP6V1C2, SRPX, and NT5E to better comprehend their roles in tumor progression and patient prognosis." (PMID 40463372, 2025). "We found SRPX showed differential expression between male and female tumor patients." (PMID 39175079, 2024). "For instance, SRPX mRNA expression is heightened in senescent cells but diminished in tumor cells." (PMID 38650467, 2024). "NR3C1 amplification, along with IL-6 and SRPX suppressions, were detected in tumor." (PMID 36675190, 2023). "From the PCR results of the risk-predictor genes, we speculated high expression levels of NR3C1 in tumor tissues and expressions of IL-6 and SRPX converged in paratumor tissues." (PMID 36675190, 2023). "SRPX protein expression was lowest in Grade 2 tumors and increased with tumor grade." (PMID 35454889, 2022). "Moreover, temozolomide (TMZ)-resistant tumor tissues showed highly positive SRPX staining, compared to all other tumor grades." (PMID 35454889, 2022). "Subsequent reports found that SRPX induces apoptosis via a novel ER-mediated pathway and suggest that this pathway might contribute to the suppression of tumor formation." (PMID 20406461, 2010). "The proposed mechanism of tumor suppression by SRPX is induction of apoptosis." (PMID 20964819, 2010). "SRPX-mediated apoptosis was correlated with the suppression of tumor formation." (PMID 20964819, 2010). "However, further studies are required to investigate whether SRPX can be detected in patient serum-derived EVs as a circulating tumor marker." (PMID 35454889, 2022).
tumor (continued). "However, the tumor suppression mechanism mediated by SRPX is more complicated than solely that of apoptosis induction, since a recent report shows that this gene is involved in the maturation process of autophagy induced by low serum, as studied in SRPX knock-out mouse-derived fibroblast cultures." (PMID 20964819, 2010). "Most methylation probes exhibited strong discriminatory performance between tumor and normal tissue, with median AUC of 0.834 and probes within three genes—MEIS2, NRG1, and SRPX—exhibiting sensitivities greater than 90%." (PMID 30917865, 2019). "Here, we start with three human proteins, SRPX, SRPX2 and CCDC80, involved in tumor suppression and progression, which possess a conserved region of similarity." (PMID 20964819, 2010). "Given the pivotal role of SRPX in regulating ER stress, its downregulation in UCEC likely plays a significant role in inhibiting these pro-apoptotic pathways, thereby contributing to tumor development and progression." (PMID 40463372, 2025). "Comparative expression analysis revealed that both SRPX and ADH1B were significantly downregulated in tumor tissues compared to normal bladder tissues (P < 0.05) across both training and validation cohorts, suggesting their potential protective roles in BCa pathogenesis." (PMID 41001025, 2025). "SRPX is downregulated in PC compared to normal prostate or benign prostate hyperplasia (BPH) and is one of seven candidate genes identified that exhibit reduced expression and increased promoter methylation, a pattern characteristic of tumor suppressors." (PMID 39149513, 2024).